ACSS2 (acyl-CoA synthetase short chain family member 2)
Diseases named in the same sentence as ACSS2 in open-access papers (continued):
Sharing a sentence is not in itself a finding about the gene and the disease.
melanoma (4 papers, 2018 to 2024). A malignant, usually aggressive tumor composed of atypical, neoplastic melanocytes. "What’s more, RNA-Seq analysis and a series of biochemical experiments were performed to explore the mechanism underlying the role of ACSS2 in melanoma." (PMID 38887280, 2024). "Hence, ACSS2’s contribution to melanoma cell survival and metastasis appears to be dependent on the Hippo pathway, underlining the pathway’s critical role in ACSS2-mediated melanoma progression." (PMID 38887280, 2024). "Further analysis revealed that ACSS2 augmented the invasive and migratory capabilities of melanoma cells." (PMID 38887280, 2024). "Taken together, ACSS2 is essential for melanoma cell survival and promotes cell invasion and migration, but is not necessary for cell proliferation under normal conditions." (PMID 38887280, 2024). "Under hypoxic conditions, ACSS2 expression is increased in various cancer cell lines including lung, colon, breast, and melanoma, promoting acetate uptake and lipid synthesis, thereby accelerating tumor progression." (PMID 38887280, 2024). "The ACSS2 expression was detected in melanoma cells and melanocytes at both protein and mRNA levels." (PMID 38887280, 2024). "To elucidate the mechanism by which ACSS2 knockdown hindered the development of melanoma, we employed RNA-Seq to identify the potential genes regulated by ACSS2." (PMID 38887280, 2024). "This study aimed to elucidate the role of ACSS2 in melanoma progression, with a particular focus on its impact on tumor cell viability and metastatic potential, alongside the mechanisms involved." (PMID 38887280, 2024). "Taken together, targeting the regulation of acetate metabolism by ACSS2 in melanoma shows promise as a potential therapeutic approach for treating melanoma in future." (PMID 38887280, 2024). "Taken together, we demonstrated that ACSS2 enables melanoma cell survival and tumor metastasis via the regulation of the Hippo pathway." (PMID 38887280, 2024). "Initially, it was noted that ACSS2 levels were markedly elevated in melanoma cell lines compared to normal melanocytes." (PMID 38887280, 2024). "We found that ACSS2 expression was significantly upregulated in melanoma cell lines compared to melanocyte NHEM at both the transcriptional and protein level." (PMID 38887280, 2024). "Further investigation confirmed positive role of ACSS2 in facilitating melanoma growth and metastasis in vivo." (PMID 38887280, 2024). "Despite these insights, the contribution of ACSS2 to melanoma metastasis and the mechanisms involved remain largely unexplored." (PMID 38887280, 2024). "Subsequently, preclinical xenograft and lung metastasis models were established to investigate the influence of ACSS2 on melanoma growth and metastasis in vivo." (PMID 38887280, 2024). "In summary, we demonstrated that ACSS2 knockdown dramatically suppressed melanoma cell migration and invasion, whereas promoted cell apoptosis in response to ER stress." (PMID 38887280, 2024). "Given the established connection between the Hippo pathway and melanoma progression, we hypothesized that ACSS2 could promote melanoma progression through the regulation of the Hippo pathway." (PMID 38887280, 2024). "In summary, this study demonstrated that ACSS2 may promote the growth and metastasis of melanoma by negatively regulating the Hippo pathway." (PMID 38887280, 2024). "Overall, our findings solidify that ACSS2 promotes melanoma growth and metastasis in vivo." (PMID 38887280, 2024). "Our study has proven that ACSS2 acts as a tumorigenic factor in melanoma, aggregating tumor growth and metastasis while inhibiting stress-triggered apoptosis, positioning ACSS2 as a viable therapeutic target for melanoma treatment." (PMID 38887280, 2024). "Furthermore, the administration of GA-017 to melanoma cell lines for 72 h subsequent to ACSS2 knockdown partially reversed the adverse impacts of the knockdown on cell invasion, migration, and apoptosis." (PMID 38887280, 2024).
melanoma (continued). "In addition, ACSS2 knockdown dramatically suppressed melanoma cell migration and invasion, whereas promoted cell apoptosis in response to endoplasmic reticulum (ER) stress." (PMID 38887280, 2024). "Then we investigated the effect of ACSS2 on melanoma cells survival." (PMID 38887280, 2024). "In addition, the immunofluorescence analysis showed that ACSS2 were mainly distributed in the cytoplasm in A2058 and A375 melanoma cells and a small amount can enter the nucleus, which was consistent with previous studies." (PMID 38887280, 2024). "Similarly, our research has demonstrated that ACSS2 is highly expressed in melanoma cells and contributes to their invasion and migration." (PMID 38887280, 2024). "Following the hypothesis that ACSS2 could be a pivotal enhancer of melanoma progression, we established melanoma cell lines with stable ACSS2 knockdown through lentiviral transfection (A2058 and B16F10)." (PMID 38887280, 2024). "Hence, ACSS2’s contribution to melanoma cell invasion, migration and survival and tumor metastasis appears to be dependent on the Hippo pathway." (PMID 38887280, 2024). "Given this, we supposed that ACSS2’s role in EMT could be crucial for melanoma’s invasive and metastatic capabilities." (PMID 38887280, 2024). "To verify whether ACSS2’s pro-oncogenic effects in melanoma were mediated via the Hippo pathway, we employed GA-017, a LATS1/2 inhibitor, to deactivate this pathway." (PMID 38887280, 2024). "Collectively, these data demonstrate that ACSS2 is upregulated in melanoma." (PMID 38887280, 2024). "Firstly, we found that ACSS2 was upregulated in most melanoma cell lines compared with melanocytes." (PMID 38887280, 2024). "Moreover, while ACSS2 minimally influenced melanoma cell viability and colony formation, its suppression notably promoted apoptosis in melanoma cells under ER stress inducer TM." (PMID 38887280, 2024). "The phenomenon disclosed that ACSS2 could confer resistance of melanoma cells to apoptosis triggers especially under stressful circumstance." (PMID 38887280, 2024). "Likewise, our findings established that ACSS2 knockdown suppressed EMT in melanoma cells." (PMID 38887280, 2024). "Targeting ACSS2 may be a promising target for melanoma treatment." (PMID 38887280, 2024). "These outcomes suggest that ACSS2 may influence melanoma metastasis via EMT regulation." (PMID 38887280, 2024). "ACSS2 may promote the growth and metastasis of melanoma by negatively regulating the Hippo pathway." (PMID 38887280, 2024). "Consequently, ACSS2 may influence cell migration and invasion as well as tumor metastasis in melanoma through the regulation of EMT." (PMID 38887280, 2024). "However, the function of ACSS2 is still largely a black box in melanoma." (PMID 38887280, 2024). "Consequently, ACSS2 may serve as a promising target for melanoma treatment." (PMID 38887280, 2024). "The CCK8 assay revealed that melanoma cell viability was not significantly altered by ACSS2 suppression." (PMID 38887280, 2024). "Collectively, these findings suggest that ACSS2 is not critical for melanoma cell proliferation under normal conditions." (PMID 38887280, 2024). "Four DNFA enzymes – SCD, FASN, ACLY and ACSS2 – exhibit the highest levels of mRNA expression in skin cutaneous melanoma (SKCM) compared to other tumor types, whereas expression of ACACA is less elevated in melanomas." (PMID 31316083, 2019). "Therefore, we speculate that ACSS2 may promote EMT process by negatively regulating the Hippo pathway, thus promoting melanoma metastasis." (PMID 38887280, 2024). "Furthermore, treating melanoma cell lines with GA-017 for 72 h after siRNA-induced ACSS2 knockdown partially mitigated the knockdown’s negative effects on cell apoptosis, invasion and migration." (PMID 38887280, 2024). "Therefore, we suppose that ACSS2 may promote melanoma growth by regulating cell death rather than cell proliferation." (PMID 38887280, 2024).
melanoma (continued). "Furthermore, immunohistochemical analysis was employed to examine ACSS2 expression in TMA and we found that ACSS2 expression was drastically increased in melanoma in comparison with nevus, but was comparable between primary melanoma tissues and metastatic melanoma tissues." (PMID 38887280, 2024).
non-small cell lung carcinoma (4 papers, 2021 to 2025). A group of at least three distinct histological types of lung cancer, including non-small cell squamous cell carcinoma, adenocarcinoma, and large cell carcinoma. "In non-small-cell lung cancer, the expression levels of ACSS2 phosphorylated at S659(ACSS2-pS659) in 303 surgical specimens were analyzed by immunohistochemistry." (PMID 35798917, 2022). "In non-small cell lung carcinoma cells ACSS2 showed increased Ser659 phosphorylation, a modification that stimulates ACSS2 nuclear translocation, when compared to the surrounding non-cancerous lung tissue." (PMID 33917812, 2021).
renal carcinoma (4 papers, 2022 to 2025). A carcinoma arising from the epithelium of the renal parenchyma or the renal pelvis. "Inhibition of ACSS2 led to an interruption of the PI3K/AKT signaling cascade, thereby restraining renal carcinoma cell proliferation, migration, and invasion." (PMID 38887280, 2024).
Anxiety (3 papers, 2022 to 2024). Intense feelings of nervousness, tension, or panic often arise in response to interpersonal stresses. "Although it has been shown that ACSS2 promotes neuronal differentiation and memory, knockout ACSS2 mice do not already cause severe behavioral changes compared to non-knockout mice and show similar levels in terms of exercise, coordination, body weight, and anxiety." (PMID 35740562, 2022).
breast tumors (3 papers, 2017 to 2025). "Furthermore, ACSS2 expression was positively correlated with breast tumour stage and patient survival." (PMID 40381373, 2025). "However, some studies have shown that reducing ACSS2 can promote tumor progression and promoting ACSS2 expression can inhibit the growth of breast tumors." (PMID 35740562, 2022). "To further investigate the role of ACSS2 expression in acetate utilization for lipogenic AcCoA, we performed U-13C-acetate tracing in a set of six cancer cell lines originating from cervical (HeLa), lung (A549), pancreatic (AsPC-1), and breast tumors (MDA-MB-231, MDA-MB-468, and BT-474)." (PMID 28099844, 2017).
Cognitive impairment (3 papers, 2022 to 2024). Abnormal cognition is characterized by deficits in thinking, reasoning, or remembering. "Taken together, these results suggest that supplementing ACSS2 substrate alleviates the cognitive impairment in aged 5 × FAD mice." (PMID 37438762, 2023). "Given the direct correlation between synaptic plasticity and cognitive impairment in AD, therapeutic strategies built on “ACSS2/histone acetylation/glutamate receptor” will provide novel perspectives for the treatment of AD." (PMID 37438762, 2023). "ACSS2 is a key molecular switch of cognitive impairment and that targeting ACSS2 or acetate administration may serve as a novel therapeutic strategy for the treatment of intermediate or advanced AD." (PMID 37438762, 2023). "Of note, we showed that supplementing acetic acid precursor glyceryl triacetate (GTA), the substrate of ACSS2, restored histone acetylation and glutamate receptor expression, leading to improved synaptic plasticity and ameliorated cognitive impairment in late-stage 5 × FAD mice." (PMID 37438762, 2023). "Furthermore, the cognitive impairment phenotype and the decreased ACSS2 expression could be transmitted to germ‐free mice through FMT." (PMID 38334013, 2024). "Given that ACSS2 requires acetate for nuclear Acetyl-CoA production and sodium butyrate is an HDAC inhibitor, it is highly plausible that acetate and butyrate supplementation may improve cognitive impairments via increasing histone acetylation." (PMID 35902549, 2022).
esophageal cancer (3 papers, 2022). A primary or metastatic malignant neoplasm involving the esophagus. "For example, metastatic bladder cancer and esophageal cancer with a high expression of ACSS2 are more prone to developing cisplatin resistance, while the use of ACSS2 inhibitors in culture medium can reduce the drug resistance developed during cisplatin treatment." (PMID 35740562, 2022). "ACSS2 can accelerate the recurrence of esophageal cancer patients and induce cisplatin resistance." (PMID 36106333, 2022). "In brief, ACSS2 targets in patients with esophageal cancer may create superior survival benefits." (PMID 36106333, 2022). "In esophageal cancer cells and the mouse esophagus, knockout of either NRF2 or ACSS2 reduced ACSS2 expression, which subsequently decreased acetyl-CoA and ATP levels." (PMID 35798917, 2022).
fibrosarcoma (3 papers, 2021 to 2025). A malignant mesenchymal fibroblastic neoplasm affecting the soft tissue and bone. "We previously shown in mice that exogenous acetate augments growth and metastasis of flank tumors derived from fibrosarcoma-derived HT1080 cells in an Acss2/HIF-2 dependent manner." (PMID 36862715, 2023). "We have shown that Acss2 augments stress signaling by HIF-2 in fibrosarcoma (HT1080) and hepatocarcinoma (Hep3B) derived cell lines subjected to oxygen or glucose deprivation." (PMID 36862715, 2023). "Acetate supplementation has been shown to increase cell proliferation both in vivo and in vitro through ACSS2 and HIF-2 pathway in a fibrosarcoma cell line, where ACSS2 translocates into nucleus and acetyl-CoA increases HIF-2 acetylation thereby increasing growth and proliferation." (PMID 33937302, 2021).
Sepsis (3 papers, 2023 to 2024). Sepsis is defined as life-threatening organ dysfunction caused by a dysregulated host response to infection. "ACSS2-deficient mice were resistant to the renal damage and inflammation associated with LPS-induced sepsis." (PMID 38515158, 2024). "Our results suggest that ACSS2 is a pro-pathogenic mediator of cell pyroptosis of RTECs and renal inflammation in sepsis-induced AKI." (PMID 38515158, 2024). "Overall, our results suggested that ACSS2 is a mediator of pyroptotic cell death of RTECs and renal inflammation in sepsis-induced AKI." (PMID 38515158, 2024). "To further probe the mechanisms by which ACSS2 modulates pyroptosis in the establishment of kidney damage in the mouse LPS-induced sepsis model, we performed RNA sequencing (RNA-seq) and bioinformatics analyses." (PMID 38515158, 2024). "In the present study, we also found that the level of ACSS2 protein was increased in RTECs of LPS-induced sepsis mice relative to RTECs from vehicle-treated mice." (PMID 38515158, 2024). "In terms of the mechanism by which ACSS2 contributed to the induction of RTEC injury by sepsis, we demonstrated that ACSS2 regulates NLRP3-mediated caspase-1 activation and pyroptosis through the KLF5/NF-κB pathway." (PMID 38515158, 2024). "For example, mice genetically lacking ACSS2 exhibited decreased cleavage of GSDMD in RTECs during the induction of sepsis, suggesting that GSDMD is a downstream effector of ACSS2 in the process of cell pyroptotic death during sepsis-induced AKI." (PMID 38515158, 2024). "This protection of RTECs from LPS-mediated inflammation by pharmacological and genetic inhibition of ACSS2 is consistent with a model in which ACSS2 overexpression is a factor leading to renal injury in sepsis." (PMID 38515158, 2024). "Further studies are needed to understand the distinct roles of ACLY and ACSS2 in EC dysfunction during sepsis." (PMID 37414769, 2023). "To further clarify whether ACSS2 contributed to the inflammatory responses to sepsis in kidney cells, we investigated the influence of ACSS2 activity on the ability of LPS to increase expression of pro-inflammatory cytokines in HK-2 cells." (PMID 38515158, 2024). "However, to this point, few studies have investigated the pathophysiological relationship between ACSS2 and pyroptosis in sepsis-induced kidney injury." (PMID 38515158, 2024). "Thus, we concluded that ACSS2 promotes pyroptotic cell death of RTECs in the sepsis-induced model of AKI via the KLF5/NF-κB pathway." (PMID 38515158, 2024). "This suggests that ACSS2 may play an important role in sepsis." (PMID 39262873, 2024). "The major finding in the present study was that ACSS2 was found to act as a critical regulator of activation of the NLRP3 inflammasome and pyroptosis in RTECs in vitro and in vivo LPS-induced sepsis models of AKI." (PMID 38515158, 2024). "Therefore, we concluded that ACSS2 deletion mitigated the activation of the NLRP3 inflammasome and decreased pyroptosis in RTECs of the mouse LPS-induced sepsis model." (PMID 38515158, 2024).
steatosis (3 papers, 2017 to 2025). Increased lipid within the cytoplasm of cells. "The loss of hepatic ACSS2 exacerbates steatosis and reduces the expression of fatty acid oxidation-related genes." (PMID 40723896, 2025). "Suppression of Acss2 in the liver after HFD feeding was reported previously, and others have reported mice lacking Acss2 are protected from steatosis induced by DIO." (PMID 35406736, 2022).
type 1 diabetes (3 papers, 2021 to 2024). "Insulin also positively regulated ACSS2 expression, while streptozotocin treatment to induce type I diabetes and decrease insulin levels decreased ACSS2 expression." (PMID 33917812, 2021). "In addition to the clinical applications of D-mannose in treating cancer, urinary infections, type 1 diabetes, and diabetic wounds, we also support the potential of D-mannose as a therapeutic strategy for depression and other neuropsychiatric disorders through its actions on ACSS2." (PMID 37914710, 2023).
adenoma (2 papers, 2024 to 2025). A neoplasm arising from the epithelium. "It is possible that as the adenoma progresses to carcinoma and acquires more mutations, these will further alter ACSS2 expression and sensitivity to its inhibition." (PMID 38464238, 2024). "Targeting ACSS2 may be a promising therapeutic approach to target KRAS G12V mutant adenomas and/or early-stage CRC." (PMID 40131933, 2025). "Finally, with respect to the clinical utility of our findings, it is possible that, as an adenoma acquires more mutations and progresses to carcinoma, the unique sensitivity of KRAS G12V cells to ACSS2 inhibition may diminish." (PMID 40131933, 2025). "Therefore, increased ACSS2 expression in G12V cells and their inherent increased utilization of acetate may favor KRASG12V adenoma formation and continuous growth in the hypoxic colorectal environment." (PMID 38464238, 2024). "Finally, ACSS2 plays a critical role in early KRAS G12V adenoma development, unlike in KRAS G12D adenomas." (PMID 40131933, 2025).
cervical cancer (2 papers, 2021 to 2024). A primary or metastatic malignant neoplasm involving the cervix. "Quantitative RT-PCR analysis confirmed that ACSS2 expression was significantly upregulated in human cervical cancer cells." (PMID 34206705, 2021). "We further tested the mRNA levels of ACSS1~3 in multiple cervical cancer cells and our results revealed that the expression of ACSS2 was higher than the other two genes in Hela and CaSki cells." (PMID 34206705, 2021). "Furthermore, in cervical cancer, ACSS2 expression positively correlates with PD-L1 expression and is closely associated with infiltration by tumor-associated fibroblasts and tumor-associated macrophages." (PMID 38887280, 2024). "To confirm the importance of ACSS2 in cervical cancer, we compared the levels of ACSS1~3 in the TPM of the female genital tract and the results showed that ACSS2 was abundant in the cervix." (PMID 34206705, 2021).
colorectal adenocarcinoma (2 papers, 2024 to 2025). The most common type of colorectal carcinoma. "Our results suggest the potential utility of targeting ACSS2 in KRAS G12V colorectal adenocarcinoma." (PMID 40131933, 2025). "Our results suggest the potential utility of targeting ACSS2 in KrasWT/G12V colorectal adenocarcinoma, which could have implications for the development of new cancer therapies." (PMID 38464238, 2024).